IL1B (interleukin 1 beta)
Diseases named in the same sentence as IL1B in open-access papers (continued):
Sharing a sentence is not in itself a finding about the gene and the disease.
chronic kidney disease (continued). "Consequently, renal inflammation is attenuated, as indicated by lower IL-1β and IL-18 concentrations, ultimately leading to improved renal function in rats with chronic kidney disease, as reflected by a significant reduction in Scr, BUN levels, and ACR." (PMID 40822454, 2025). "Therefore, studies have shown that inhibition of IL-1β increases insulin sensitivity, improves renal function, and reduces cardiovascular complications in patients with chronic kidney disease." (PMID 38257150, 2024). "Male rat mesangial cells exhibit naturally higher baseline levels of fibronectin, TNF- α, and interleukin-1 beta (IL-1β) compared to female cells, which may play a role in the quicker advancement of chronic renal disease in males." (PMID 39124622, 2024). "The renoprotective effects of SSR in rats with chronic renal failure may be related to its inhibition of hypoxia via the IL-1β/c-Myc pathway." (PMID 34211565, 2021). "Indeed, EET-A has previously been demonstrated to decrease renal inflammatory cell infiltration and levels of monocyte chemoattractant protein-1 (MCP-1), TNF-α, IL-6, and IL-1β in acute and chronic kidney disease models." (PMID 33801911, 2021). "NLRP3, IL-1β, and IL-18 are significantly upregulated in chronic kidney disease patients undergoing hemodialysis treatment, indicating that the NLRP3 inflammasome may be activated in and contribute to chronic inflammation in CKD." (PMID 32660446, 2020). "In addition, in chronic kidney disease, serum levels of inflammatory markers, such as IL-6, IL-8, IL-1β, are increased." (PMID 28542419, 2017). "In addition, high levels of IL-1β in diabetic patients can also induce pyrodeath of renal foot process cells, and the level of IL-1β in diabetic nephropathy patients is closely related to the level of urinary protein and the time of progression to end-stage renal disease." (PMID 38725443, 2024). "Indeed, inhibition at the terminal level of the NLRP3 inflammasome axis, IL-1β, with canakinumab (a monoclonal IL-1β antibody) reduced cardiovascular events in the recent CANTOS trial, but disturbingly also led to a loss in eGFR in subjects with chronic kidney disease." (PMID 35048962, 2022). "We show that theracurmin attenuates NLRP3 inflammasome activation in the heart and reduces circulating IL-1β levels, illustrating a cardio-protective effect of the compound and the potential therapeutic benefits of a theracurmin-based treatment strategy in the setting of chronic kidney disease." (PMID 28000751, 2016). "Patients with chronic kidney disease (CKD) exhibit elevated CD14++CD16+ pro-inflammatory monocytes in bone marrow alongside heightened systemic levels of IL-6, IL-1β, and TNF-α, suggesting persistent innate immune activation." (PMID 40746537, 2025). "In experimental chronic kidney disease (CKD), IL-1β facilitates atrial fibrosis and increases vulnerability to atrial fibrillation, effects that are mitigated by IL-1β blockade." (PMID 41011058, 2025). "In the Chronic Renal Insufficiency Cohort (CRIC) study, biomarkers of inflammation (IL-1β, IL-1 receptor antagonists, IL-6, TNF-α, CRP, and fibrinogen) were negatively associated with renal function and positively associated with proteinuria." (PMID 39126619, 2024). "Since IL-1β appears to be driving CPPD arthritis, we treated two patients with chronic CPPD arthritis and end-stage renal disease on haemodialysis with the IL-1β receptor antagonist anakinra." (PMID 38756932, 2024). "Effects of Shenkang injection (SKI) on the levels of CRP, IL-1β, IL-6, TNF-α, IL-4,and IL-10 in serum of chronic renal failure rats*." (PMID 35674582, 2022). "Furthermore, studies have shown that NLRP3 activation has been implicated in an inflammasome complex which involves triggering the NF-κB pathway with release of IL-1β all of which may play a significant role in CaNL and eventually in the development of chronic kidney disease." (PMID 33802660, 2021).
chronic kidney disease (continued). "Interestingly, TNF-α, IFN-γ, and IL-1β levels remained nonstatistically associated with death in the multivariable analysis that included the entire patient cohort after adjusting for age, chronic kidney disease, and receipt of immunomodulatory medications." (PMID 33232303, 2021). "While IL-1β mediates podocyte injury and renal inflammation, NLRP3 is involved in the pathogenesis of chronic kidney disease." (PMID 33133213, 2020). "Clinical trials investigating canakinumab, an antibody targeting IL-1β, noted decreased rates of cardiovascular events in atherosclerosis patients with chronic kidney disease (CKD) without impacting renal function." (PMID 38740765, 2024). "However, a clinical trial suggested that canakinumab, an inhibitor of IL-1β, did not provide significant clinical benefits or cause substantial harm in patients with chronic kidney disease (CKD)." (PMID 39337537, 2024). "Proinflammatory cytokines such as TNFα, IL-1β, and IL-6 are potent stimuli for the FGF-23 secretion by osteocytes and have been demonstrated to play a role in upregulating intact FGF23 in experimental models in vivo of both acute kidney injury and chronic kidney disease." (PMID 37893926, 2023). "In chronic renal failure rats, TFA administration improved renal injury, remodeled gut microbiota dysbiosis, including regulated intestinal-derived metabolites such as D-serine, D-amino acid oxidase, L-serine, and serine racemase, suppressed the levels of pro-inflammation (TNF-α and IL-1β)." (PMID 35123452, 2022). "Plasma levels of interleukin (IL)-1β, IL-1 receptor antagonist (IL-1RA), IL-6, tumor necrosis factor (TNF)-α, transforming growth factor (TGF)-β, high-sensitivity C-Reactive protein (hs-CRP), fibrinogen and serum albumin were measured in 3,939 Chronic Renal Insufficiency Cohort study participants." (PMID 25909952, 2015). "Patients with chronic kidney disease (CKD) display higher serum levels of oxLDL, characterized by an hyperinflammatory phenotype of monocytes accompanied by an increased production of pro-inflammatory cytokines (i.e., TNF-α, IL-1β and IL-6)." (PMID 36979747, 2023). "The role of NLRP3 has been underlined in various causes of acute and chronic kidney diseases and NLRP3 inhibition or IL-1β blocking may protect from AKI and AKI to CKD transition." (PMID 34099830, 2021). "An amount of 15% w/w orally in the feed of flaxseed for 33 days significantly reduced the renal inflammation (IL-1β, IL-6, and NF-κB) in STZ-induced diabetic rats with or without chronic kidney disease." (PMID 37685162, 2023). "The urinary IL-1β level has been reported to be elevated in patients with APN, and urinary KIM-1 is a sensitive biomarker for AKI and is not influenced by UTIs or chronic kidney disease." (PMID 23319831, 2012). "It is well known that FGF23 circulating levels are upregulated in chronic kidney disease, and we have shown recently that FGF23 per se does not exert a pro-inflammatory effect on the “healthy” bronchial epithelium, whereas the COPD epithelium shows increases in IL-1β when stimulated with FGF23." (PMID 37763754, 2023). "IL-1β-mediated upregulation of SLC7A5 expression without any obvious external stimuli (e.g., TLR triggering) could explain the increase in SLC7A5 seen in monocytes from patients with inflammatory diseases, such as RA and end-stage renal diseases (data not shown)." (PMID 29422900, 2018). "Moreover, macrophages from chronic kidney disease (CKD) patients exposed to the uremic toxin IS displayed inflammation through activation of the AhR/NF–κB/MAPK cascade, in a process that induced the mature IL-1β production without activating NLRP3 inflammasome." (PMID 39211042, 2024).
gingivitis (86 papers, 2012 to 2026). A disorder involving inflammation of the gums; may affect surrounding and supporting structures of the teeth. "The proinflammatory cytokines IL-6 and IL-1β were prominently associated with gingivitis, suggesting that the levels of these cytokines could predict or confirm oral inflammation." (PMID 36163488, 2022). "Bacteria-induced inflammation of the gingiva, so-called gingivitis, may also cause elevated levels of IL-1β in the saliva." (PMID 34121926, 2021). "Therefore, we can conclude that IL-1b can be used as a diagnostic marker of inflammation in patients with gingivitis." (PMID 24790719, 2014). "Salivary cytokine profile differed according to oral condition: caries was associated with reduced IL-4, IL-10, and IFN-γ; gingivitis with elevated IL-1Ra and RANTES; and both conditions with increased IL-1β (p-value < 0.05)." (PMID 41505053, 2026). "Clinical interventions for severe gingivitis have demonstrated reductions in oral TNF-α and CRP, while advanced gingivitis also correlates with elevated IL-1β in saliva." (PMID 40558433, 2025). "In experimental gingivitis, IL-1β levels decreased by the tenth day but returned to baseline after 14 days of oral hygiene instructions." (PMID 40265034, 2025). "With respect to gender, female gingivitis samples showed high levels of IL-1β with respective control." (PMID 38086426, 2024). "They made an ointment cream and tested it on an animal model of gingivitis by looking at gene expression of NF-κB, IL-1β, IL-6, p38, and TNF-α." (PMID 38978754, 2024). "Their findings are different from the results of the present study because the present study revealed significant changes in salivary IL-1β levels in both groups following the anti-inflammatory treatment and improvements in gingivitis (P = 0.0001)." (PMID 36973728, 2023). "A study revealed that matrix-metalloproteinase 3 (MMP-3), MMP-8, and IL-1β in gingival crevicular fluid and whole saliva of gingivitis patients remained insignificantly altered over 8 weeks of OIs use." (PMID 36834421, 2023). "The expression of proinflammatory markers such as TNF-α, IL-6, IL-8, IL-17, and IL-1β has been reported to be detected in the gingival crevicular fluid after gingivitis and can also be detected in saliva." (PMID 36998066, 2023). "Few studies have investigated the impact of experimental gingivitis or treatment on IL-1β, IL-8, or MCP-1 levels." (PMID 38004199, 2023). "The disproportionate salivary levels of IL‐1β and IL‐4 in patients with gingivitis are likely to be the molecular signature of oral inflammation, possibly induced by increasing phosphate consumption." (PMID 35141474, 2022). "When comparing ANXA-1 and IL-1β levels, Hassan and colleagues found that the pregnant gingivitis group exhibited nearly 2-fold higher ANXA-1 levels compared with the non-pregnant gingivitis group." (PMID 36432584, 2022). "In patients with gingivitis, levels of IL-1β, IL-6, IL-7, IL-13, IL-17, IL-21 and MIP-3α in gingival crevicular fluid in the Sg group were lower in comparison with the Dg group." (PMID 33417619, 2021). "Contact with dental materials can, in fact, cause an inflammatory response with over-production of inflammatory markers such as IL6, IL-8, IL1β, IL-18, all of which play major roles gingivitis and periodontal destruction." (PMID 33211211, 2021). "The objective of this study is to evaluate the salivary concentrations of IL-1β, IL-6, IL-8, IL-10, TNFα and IL-12p70 of DS individuals and compare to cerebral palsy (CP) and normoactive patients (all with gingivitis)." (PMID 32509226, 2020). "IL-1β levels in gingival crevicular fluid (GCF) of patients with CP are significantly higher than those in patients with gingivitis and periodontally healthy individuals." (PMID 30755772, 2019).
gingivitis (continued). "The two most important findings were that using green tea chewing gum significantly decreased the API and SBI indices that are indicators of gingivitis, as well as the level of IL-1β as a pre-inflammatory cytokine in salvia." (PMID 27284561, 2016). "Of the 10 studies that were included to determine the difference in IL-1β levels, only 3 studies showed differences in IL-1β levels between healthy subjects and patients with gingivitis." (PMID 28074077, 2016). "Outstanding among their results were that the individuals who were subject to experimental gingivitis presented higher IL-1β and lower IL-8 levels at 4 weeks than individuals with persistent gingivitis." (PMID 24790719, 2014). "Having reviewed the literature, we can confirm that IL-1b is the most commonly studied interleukin by authors who have tried to establish inflammation markers in gingivitis." (PMID 24790719, 2014). "The most commonly studied interleukin is IL-1β and most authors agree that it is higher in the saliva and/or crevicular fluid of patients with gingivitis." (PMID 24790719, 2014). "Salivary cytokines may be more reflective of local inflammation in the oral cavity than systemic inflammation, as suggested by elevated salivary IL‐1β, IL‐6, and IL‐8 levels in the presence of gingivitis in otherwise healthy children and adolescents." (PMID 40547317, 2025). "One salivary cytokine that has been studied in caries and gingivitis is interleukin-1 beta (IL-1β), indicating that it may be involved in the development of such conditions." (PMID 39358612, 2024). "The concentrations of IL-1β, IL-6, IL-8 and IL-10 were elevated in the presence of gingivitis." (PMID 36163488, 2022). "The gingivitis group showed higher levels of IL-1β, MMP-8, and Pg compared to the healthy group." (PMID 34001101, 2021). "C3a is closely related to gingivitis and can modulate IL‐1β secretion in human monocytes." (PMID 32794619, 2020). "The hypothesis of the study was that individuals with DS present higher levels of IL-1β, IL-6, IL-8, IL-10, TNFα and the p70 subunit of interleukin-12 (IL-12p70) cytokines when compared to individuals with CP and normoactive, all with gingivitis." (PMID 32509226, 2020). "A strong correlation was observed between baseline samples and samples collected 14 days after resolution of experimental gingivitis (day 24) of IL-1β (R = 0.66, p < 0.001), IL-1Ra (R = 0.85, p < 0.001), IL-8 (R = 0.79, p < 0.001), and VEGF (R = 0.80, p < 0.001)." (PMID 28839521, 2017). "Thus, the aim was to quantify selected chemokines and cytokines associated with early stages of gingivitis (i.e. vascular endothelial growth factor [VEGF], IL-8, monocyte chemoattractant protein [MCP-1], IL-1β, and IL-1 receptor antagonist [IL-1Ra])." (PMID 28839521, 2017). "IL-1β is recognized as a pathologic and pre-inflammatory factor since its level increases in salvia and gingival crevicular fluid during the progression of gingivitis." (PMID 27284561, 2016). "Owing to the slight differences in IL-1β levels between healthy and gingivitis sites, it is difficult to use them as indicators or predictors for disease initiation from healthy status to gingivitis." (PMID 28074077, 2016). "However, to our knowledge, our study is the first to include histological assay results when reporting the effects of omega-3 supplementation on experimental gingivitis biomarkers (IL-1β, TNF-α)." (PMID 24711890, 2014). "Similarly, after adjusting for age, sex, body mass index, and gingival redness, the daily dietary phosphate consumption was strongly correlated with the salivary level of IL‐1β; it was inversely correlated with the salivary level of IL‐4 in patients with gingivitis." (PMID 35141474, 2022). "Therefore, the majority of the studies that have analyzed IL-1b in saliva and/or the crevicular fluid of patients with gingivitis are in agreement that this interleukin is a reliable marker of the level of inflammation in gingivitis." (PMID 24790719, 2014).
gingivitis (continued). "Moreover, as far as the other interleukins studied are concerned, there is no clear consensus among the authors.Conclusion: There is sufficient evidence to suggest that IL-1β in saliva and/or crevicular fluid can be used as a marker of the degree of inflammation in gingivitis." (PMID 24790719, 2014). "In both ENDS users and NS with gingivitis, GCF IL-1β levels were significantly higher at baseline (p<0.05) than at T1 and T2; however, the difference was not significant between ENDS users and NS at each time interval." (PMID 38988743, 2024). "A gel preparation of Eug-NE was studied as an anti-inflammatory, analgesic, and anesthetic in treating induced gingivitis in rats and showed significant results by reducing tumor necrosis factor-α (TNF-α) and IL-1β." (PMID 37235301, 2023). "Further, the combination of IL-1β and MMP-8 can be used to discriminate gingivitis patients from healthy subjects." (PMID 34001101, 2021). "In their study, levels of interleukin (IL)-1β, IL-6, MMP-8, and PGE2 from 40 periodontally healthy subjects and 40 subjects with gingivitis were measured." (PMID 33615769, 2021). "The combination of IL-1β and MMP-8 exhibited the best ability to discriminate gingivitis from healthy subjects (AUC = 0.84)." (PMID 34001101, 2021). "IL-1β, IL-6, IL-7, IL-13, IL-17, IL-21 and MIP-3α in GCF of T2DM patients with gingivitis were significantly downregulated by statins treatment." (PMID 33417619, 2021). "IL-1β, MMP-8, and Pg levels were shown to be significantly different between the gingivitis group and the healthy group." (PMID 34001101, 2021). "On the other hand, elevated IL-1β, steady IL-1Ra, and decreased MCP-1 levels have been observed in gingival crevicular fluid samples in experimental gingivitis, which conflicts with data from this report." (PMID 28839521, 2017). "Salivary IL-1β, IL-1Ra, and VEGF levels decreased after 10 days’ development of experimental gingivitis and reached baseline levels at the end of the 2-week resolution period." (PMID 28839521, 2017). "Similarly, the combination of IL-1β and MMP-8 showed an AUC of 0.84 in differentiating gingivitis from healthy individuals." (PMID 40283051, 2025). "Lowered gingivitis and plaque scores, lessened GCF volume and BOP, and lowered IL-1β concentration." (PMID 38398870, 2024). "Following this upregulation in the early stage, Il6 and Tnfsf11 markedly increased in the PRT in IP, but Tnf and Il1b showed no apparent changes after the gingivitis phase." (PMID 38548743, 2024). "IL1B, CXCR4 mRNA were up-regulated in gingivitis samples compared with normal tissues (P < .05)." (PMID 37986309, 2023). "Moreover, the combination of IL-1β and MMP-8 can be used to discriminate gingivitis subjects from healthy subjects." (PMID 35368315, 2022). "Similarly, significantly higher IL-1β and MMP-8 levels were also found in women with gingivitis compared to healthy pregnant women." (PMID 36432584, 2022). "Also, the combination of IL-1β and MMP-8 can be used to differentiate between gingivitis patients and healthy subjects." (PMID 35265136, 2022). "However, among the pregnant subpopulations, women with gingivitis had significantly higher ANXA-1 and IL-1β levels than healthy pregnant women." (PMID 36432584, 2022). "While in their study IL-1β failed to discriminate gingivitis from the healthy condition, in the present study, this cytokine was the only statistically significant discriminator identified after a follow-up period of eight weeks." (PMID 33615769, 2021). "Three of the studies analyzed this interleukin in non-experimental gingivitis, the authors finding that IL-1b was higher in patients with gingivitis when compared to those of the control group and that these results were statistically significant." (PMID 24790719, 2014). "A lack of effect on IL-1β was observed also for patients with gingivitis." (PMID 40944222, 2025).